MMP9 (matrix metallopeptidase 9)
Diseases named in the same sentence as MMP9 in open-access papers (continued):
Sharing a sentence is not in itself a finding about the gene and the disease.
tumor (continued). "Extracellular matrix degradation is an indispensable step in tumor metastasis and invasion, which is mainly mediated by the balance between selected MMPs, such as MMP9 and MMP2." (PMID 30453504, 2018). "Remodeling tumor stroma and pro-angiogenesis: IL-33 markedly stimulates myofibroblasts to produce several types of extracellular matrix components including MMP2, MMP9, and growth factors associated with CRC tumor growth, progression and metastasis." (PMID 30547011, 2018). "In HCC cell lines, miR-199a was found to suppress tumor proliferation and to induce apoptosis and cell cycle arrest by regulating the expression of matrix metallo-proteinase-9 (MMP-9), frizzled type 7 receptor (FZD7), and hypoxia-inducible factor-1α (HIF1α)." (PMID 29337905, 2018). "MMP-9 regulates the microenvironment around the tumor and increases the concentration of vascular endothelial growth factor (VEGF) that regulates angiogenesis." (PMID 29520667, 2018). "This type of remodeling has been associated with invasive CCs and overexpression of MMP-2 and MMP-9 is also correlated with a worse prognosis in patients with this tumor type." (PMID 29770331, 2018). "These showed that PI3K/Akt/NF-κB/MMP-9 signaling pathway is involved in the regulation of tumor cell proliferation, migration, heterogeneous adhesion, and ECM and BM degradation." (PMID 30046339, 2018). "We finally confirmed that in an invasive scenario, ALCAM and MMP-9 are important actors at the invasive front of the tumor." (PMID 29682175, 2018). "We found that the high mRNA expression of MMP9 correlated with an unfavorable clinical outcome of ccRCC patients, after adjusting for tumor location, stage and patient age, gender and race." (PMID 30013825, 2018). "MMP-9 levels in the tumor tissue extracts had also increased significantly (median values 89.9 and 133.5 ng/mL, respectively; p < 0.01)." (PMID 29520667, 2018). "MMP-2 and MMP-9 are two important ECM degradation enzymes that promote tumor invasion and metastasis via breaking basement membrane structure and degrading ECM." (PMID 30479571, 2018). "NF-κB target gene encoding proteins such as MMP-9, VEGF, MCL-1, XIAP, C-FLIP, and Cyclin-D1, promote metastasis, angiogenesis, antiapoptosis, and proliferation in HCC leading to tumor progression." (PMID 29535278, 2018). "In the current study, we focused on the use of the syngeneic NeuT tumor model to assess the effects of MMP-9 inhibition on the adaptive immune response." (PMID 30500835, 2018). "Here we demonstrated that TIPE2 suppressed tumor aggressiveness via inhibiting Rac1, which subsequently decreased the expression of uPA and MMP9 in PTC cells." (PMID 30186591, 2018). "We demonstrate that SMG inhibits expression of integrin α6β4, MMP9 and Met72, leading to significant reduction in cell adhesion and invasiveness in vitro and tumor metastasis to lungs in vivo." (PMID 29491429, 2018). "Previous research has implicated TAFs in recruitment of pro-angiogenic immune cells promoting tumor angiogenesis via a mechanism mediated by matrix metalloproteinase MMP9 and VEGFA." (PMID 29921235, 2018). "Immunocytochemistry analysis of tumor xenograft demonstrated less expression of MMP-9 in the mouse treated with EphA2-siRNA, suggesting that silencing of EphA2 gene down regulated the MMP-9 gene expression and exerted tumor inhibitory effects." (PMID 29861465, 2018). "Another study has shown that fentanyl inhibits tumor growth and cell invasion in colorectal cancer by downregulating miR-182 and MMP-9 expression using β-catenin." (PMID 29347949, 2018). "When the Chemokine C-X-C Motif Receptor Type 4 (CXCR4), whose expression can be enhanced by hypoxia, binds Stromal Cell-derived Factor 1 (CXCL12), secreted by CAFs, release of MMP-9 to the tumour microenvironment is stimulated." (PMID 29743718, 2018). "Among the members of the MMPs family, gelatinases MMP-2 and MMP-9 are considered to be the essential regulators of the tumor microenvironment." (PMID 30581847, 2018).
tumor (continued). "Studies revealed that MMP-9 is required for shift of angiogenic balance towards pro-angiogenic phase while MMP-2 contributes in tumor growth." (PMID 30344239, 2018). "The selective localization of MMPs such as MMP-9 and β-1 integrin and their shedding into EVs from tumor cells participate in localized degradation and the proteolysis of ECM during cellular migration and metastasis." (PMID 30322133, 2018). "Immunohistochemical expression of ANO1, β-catenin, MMP9, snail, and E-cadherin were observed in the cytoplasmic membrane, cytoplasm, and nuclei of tumor cells and the expression of cyclin D1 was observed in the nuclei of tumor cells." (PMID 29416639, 2018). "This process needs accumulation of growth factors in extracellular matrix by tumour cells and accumulation of active MMP9 secreted by proangiogenic monocytes." (PMID 29367702, 2018). "We previously evaluated the effects of inhibiting MMP-9 on primary tumor growth and metastasis in a CRC mouse xenograft model, HCT116." (PMID 30500835, 2018). "Immunohistochemical staining for CD31 and MMP-9 showed that tumor cell neovascularization and invasiveness in hyperacetylated tumors were lower in RAGEOV than in RAGEKD mice." (PMID 29880821, 2018). "In particular, MMP-2 and MMP-9, which selectively degrade type IV collagen, have been shown to facilitate tumor invasion and metastasis in various cancers." (PMID 29977159, 2018). "During tumor progression, the expression of matrix metalloproteinases (MMP), in particular MMP-9, significantly increases and it is associated with the alteration of BBB." (PMID 30441761, 2018). "MMP14, a membrane-type, is present at high levels in the tumor cells themselves, while MMP9, a gelatinase specific to collagens IV and V, is more often upregulated in the stroma." (PMID 29996539, 2018). "We have previously shown that a highly selective and potent allosteric antibody inhibitor of MMP-9 decreased primary tumor growth and metastasis in xenograft mouse models." (PMID 30500835, 2018). "Compared with the model group, the protein levels of MMP-9 in transplanted tumor were decreased with a dose-effect relationship in the GBEE (50, 100, and 200 mg/kg) groups." (PMID 30046339, 2018). "In our opinion, this is the first comprehensive description of potential activities where MMP-2 and MMP-9 can be involved in the complicated scenario in which the mechanisms of tumor progression are correlated with unfavorable prognosis." (PMID 30060564, 2018). "Plac1 appears to be responsible for upregulating the expression of MMP2 and MMP9, which degrade the extracellular matrix to promote tumor cell invasion and metastasis." (PMID 29704427, 2018). "MMP-9 is known to play an essential role in enhancing the migration and invasive capacities of malignant tumour cells by degrading the surrounding ECM, which helps to accelerate the process of metastasis." (PMID 29973599, 2018). "In conclusion, MTs can induce the upregulation of angiogenesis-related genes, such as VEGF and MMP-9; act on ECs, SMCs, and macrophages; and result in the formation of new blood vessels to promote tumor growth, progression, and metastasis." (PMID 30139373, 2018). "Based on their previous studies, they further figured out the positive correlation between MMP-9 and angiogenesis in tumor invasiveness." (PMID 32922863, 2018). "MMP9 gene expression was determined for all the samples and it served as internal control for differentiating tumor samples from normal samples." (PMID 29371635, 2018). "In the same cell line, Uro-A downregulated the expression of matrix metallopeptidase 9 (MMP-9), a protein directly linked to tumour invasion and metastasis." (PMID 30441778, 2018). "The results of immunocytochemistry showed that GBEE (50-200 mg/kg) significantly reduced the expression of MMP-9 protein with a dose-effect relationship in the transplanted tumor." (PMID 30046339, 2018).
tumor (continued). "Recent research showed that MMP-2 and MMP-9 were expressed in iCCA and participated in tumor invasion and metastasis." (PMID 29682557, 2018). "By IHC staining, we found that PD-325901 robustly diminished MMP-9 protein expression in the tumor lesions." (PMID 29458390, 2018). "For example MMP-9 can in vivo increase the levels of endostatin in nude mice and therefore decreased vessel density and reduced tumor growth." (PMID 29316907, 2018). "Matrix metalloproteinase 9 (MMP9) plays a key role in tumor cell migration and invasion induced by various tumor-promoting cytokines and growth factors, including TNF-α and EGF33." (PMID 30042418, 2018). "Matrix metalloproteinases (MMPs), especially MMP-2 and MMP-9, are responsible for the degradation of components of the basement membrane and extracellular matrix, thereby promoting tumor invasion." (PMID 29867502, 2018). "Consistent with our in vitro experiments, analysis of NeuT tumor protein lysates showed that anti-MMP-9 treatment increases expression of CXCL10 and other T cell–stimulating factors, such as interleukin (IL)-12p70 and IL-18." (PMID 30500835, 2018). "The secretion and activation of MMP2 and MMP9 are linked with the degradation of ECM and promotion of tumor metastasis." (PMID 29558998, 2018). "Lycopene also inhibits matrix metallopeptidase protein (MMP-9) in correlation with reduction of angiogenesis, tumor invasion and metastasis." (PMID 30487390, 2018). "We show that inhibition of MMP-9, a key component of the tumor-promoting and immune-suppressive myeloid inflammatory milieu, increases T-helper cell 1 type cytokines, trafficking of effector/memory T cells into tumors, and intratumoral T-cell diversity." (PMID 30500835, 2018). "IB assay of tumor tissues revealed that XAF1 induction leads to MMP9 reduction and strongly increases both cleaved PARP and CASP3 levels in sh-Control but not sh-IRF-1 tumors." (PMID 30042418, 2018). "To further study the correlation between CTHRC1 and MMP7 as well as MMP9 in fresh primary tumour tissues, we measured the expression of CTHRC1 and MMPs by performing reverse dot blot hybridization." (PMID 29631554, 2018). "From early studies, membrane-bound MMP9 represented only a very small fraction of the enzyme, while the secreted form is more biologically relevant in tumor development." (PMID 30149671, 2018). "Microglia treated with GCM showed an induction of tumor promoter gene MMP9, concomitant with an increase in SMAD4 level." (PMID 29861845, 2018). "Despite this, qPCR experiments and in situ hybridization demonstrated that expression of matrix metalloproteinase genes (mmp9, mmp13a and mmp14b) was strongly increased in krasG12D-expressing intestinal cells, a molecular clue for invasiveness of tumor cells." (PMID 29592890, 2018). "Undoubtedly, both MMP9 upregulation and matrix protein deposition created a suitable “soil” in lung for circulating tumor cells colonization and growth." (PMID 29728125, 2018). "MMP-2 and MMP-9 are major proteolytic enzymes contributed to ECM degradation to promote tumor cell migration and invasion." (PMID 30359388, 2018). "The authors investigated the effect of ECM components on MMP-2 and MMP-9, because they are the key effectors that are involved in the degradation of the basement membrane, an important step during tumor invasion." (PMID 30301152, 2018). "Inhibition of the activity of MMP-2 and MMP-9 in tumour cells can inhibit the effects of cancer cells." (PMID 29751513, 2018). "MMP-9 in particular has been extensively studied for its effects on tumor cell invasion and angiogenesis." (PMID 29929486, 2018). "PI3K/Akt inhibition has been shown to block sonic hedgehog pathway-induced EMT, matrix MMP9 activity, and lymphangiogenesis, reducing tumor invasiveness and metastasis." (PMID 29426928, 2018). "In the tumor tissue extract analyses, baseline MMP-9 levels had a median concentration of 89.9 ng/mL (175.4) range 22.6–619.9 ng/mL." (PMID 29520667, 2018).
tumor (continued). "Scholars have confirmed that the PI3K/Akt signaling pathway can increase the level of MMP-9 through activating the NF-κB; therefore, the metastasis of tumor cells was enhanced." (PMID 30046339, 2018). "Accumulating evidence has shown the role of the PI3K/Akt pathway in the mechanisms of EPS8 associated tumor proliferation, survival and drug resistance by activating downstream targets, such as FOXM1, mTOR, MMP-9 and caspase-9." (PMID 29357910, 2018). "On the other hand we found that the concentration of MMP-9 in tissue sample extracts increased during storage with tumor samples showing the greatest change." (PMID 29520667, 2018). "In order to determine if miR-146a regulates tumor supportive gene expression in microglia, expression of MMP9 upon overexpression and knockdown of miR-146a was analyzed." (PMID 29861845, 2018). "In this study, Curcumin reduced markedly the tumor volume, along with MMP-2 and MMP-9 activity in the tumor-bearing site, and the number of metastatic nodules in vivo in contrast to the untreated control group." (PMID 29890744, 2018). "The Kiss1 gene is a tumor suppressor that codes for a protein that regulates cancer cell metastasis by suppressing matrix metalloproteinase 9 (MMP9)." (PMID 29652858, 2018). "Further, MDSCs can also directly incorporate into tumor endothelium and promote tumor angiogenesis by producing high levels of matrix metalloproteinase-9 (MMP9)." (PMID 30464804, 2018). "To address the mechanism of action of MMP-9 in NeuT tumors, we performed RNAseq gene expression analysis on tumor samples taken at study end (day 27)." (PMID 30500835, 2018). "We describe how infection-induced upregulation of miR-126-5p ablates JIP-2 expression to release cytosolic JNK to translocate to the nucleus and trans-activate AP-1-driven transcription of mmp9 to promote tumour dissemination." (PMID 29570727, 2018). "The expressions of vascular endothelial growth factor (VEGF), matrix metalloproteinase (MMP)‐2, and MMP‐9, which served as tumor promoter, were detected by Western blot." (PMID 30280514, 2018). "In this process, matrix metalloproteinases (MMP), especially MMP-2 and MMP-9, are crucial for extracellular matrix remodeling and, consequently, the tumor invasiveness." (PMID 29867502, 2018). "In those, MMP-9 increased concomitant with a decrease in ALCAM from the superficial area to the invasive front of the tumor." (PMID 29682175, 2018). "Mechanically, TIPE2 suppressed tumor invasiveness by inhibiting Rac1, which subsequently decreased the expression of uPA and MMP9." (PMID 30186591, 2018). "Western blot was used to demonstrate that Plac1 regulates the PTEN/AKT signaling pathway, which further regulates MMP2 and MMP9 to promote tumor cell invasion and metastasis." (PMID 29704427, 2018). "It has been demonstrated that Rac1 regulates various downstream effector molecules related to tumor aggressiveness, such as MMP9 and uPA." (PMID 30186591, 2018). "In contrast, it has been demonstrated that calgranulins are involved in the induction matrix-metalloproteinases, such as MMP-9, which are involved in tumor growth and angiogenesis." (PMID 29563902, 2018). "Overexpression of miR-146a resulted in decreased expression of SMAD4 together with tumor supportive gene MMP9 in microglia, and subsequently suppressed microglial migration towards GCM, possibly through regulation of SMAD4." (PMID 29861845, 2018). "CXCL8 exerts its angiogenic activity by up-regulating matrix metalloproteinase (MMP-2) and MMP-9 enzymes in tumor and endothelial cells leading to degradation of extracellular matrix which is one of pre-requisites for EC migration and organization." (PMID 30344239, 2018). "Further, we were unable to definitively determine the long-term consequences of anti–MMP-9 antibody treatment on anti-tumor immunity using this model." (PMID 30500835, 2018).
tumor (continued). "Matrix metalloproteinase-2 (MMP-2) and metalloproteinase-9 (MMP-9) degrade structural proteins of invaded tissues and play a crucial role in metastasis of tumor cells and angiogenesis." (PMID 29337896, 2018). "MMP-9, a member of the matrix metalloproteinase family and a critical player in tumor invasion, expression was also decreased in COPS3-depleted 143B and HOS cells." (PMID 29970115, 2018). "Cell migration and invasion mediated by epithelial mesenchymal transition (EMT) and matrix metalloproteinase-9 (MMP-9) within TMEs are prerequisite for tumor cells to disseminate from primary tissues." (PMID 29346311, 2018). "As one of the enzymes that specifically degrade ECM and BM, MMP-9 is also closely related to the proliferation, migration, and heterogeneous adhesion of tumor cells." (PMID 30046339, 2018). "MMP-9 can inhibit tumor development, mostly through influencing the angiogenesis, for example in the metastatic foci, of different neoplasm." (PMID 29316907, 2018). "Whatever, it seems clear that in the setting of this study, MMP-9 levels in tissue extracts from tumor and healthy mucosa increased over the period of cryopreservation." (PMID 29520667, 2018). "Functional analyses revealed that PLOD3 interacts with STAT3, thereby expressing matrix metalloproteinases (MMP-2 and MMP-9) and with urokinase plasminogen activator (uPA) to enhance tumor metastasis." (PMID 30442941, 2018). "Our data indicate that inhibition of MMP-9, a key component of the tumor-promoting and immune-suppressive myeloid inflammatory milieu, reduces tumor burden and promotes effector/memory T-cell infiltration and diversity when combined with an anti-PDL1 antibody." (PMID 30500835, 2018). "ALCAM maintained a close and inverse relation with MMP-9 at the invasive front of the tumor (p=0.004; OR 0.26)." (PMID 29682175, 2018). "Both of MMP9 upregulation and matrix protein deposition triggered matrix remodeling and created a suitable “soil” in lung tissue for circulating tumor cell colonization and growth." (PMID 29728125, 2018). "Our data show significantly upregulated levels of MMP-1, MMP2, MMP3 and MMP9 mRNA in ESCC tumor tissues compared to the adjacent normal tissues." (PMID 30241395, 2018). "Regarding MMP-9, 40 patients (37 %) had a high score in stroma compared to 17 patients (15,7 %) with a high score in tumor regions (p = 0.036, chi-square)." (PMID 29492204, 2018). "Tumor cell-derived EVs are potent stimulators of MMP-9, IL-6, and TGF-β1 and induce the secretion of extracellular EMMPRIN, which play active roles in driving immune evasion, invasion and inflammation in the tumor microenvironment." (PMID 30322133, 2018). "Matrix metalloproteinase 9 (MMP-9), an enzyme that degrades collagen IV to destroy basement membrane, has been shown to promote tumor invasion." (PMID 29682557, 2018). "It is noteworthy that resveratrol strongly suppressed TNF-β-induced activation of tumor-promoting factors (NF-κB, MMP-9, CXCR4) and epithelial-to-mesenchymal-transition-factors (increased vimentin and slug, decreased E-cadherin) in CRC cells." (PMID 30002278, 2018). "Matrix metalloproteinases MMP2 and MMP9 are involved in tumor invasion, and their protein levels were significantly downregulated at 72 h post-miRNA-agomir transfection." (PMID 29849932, 2018). "Recently, it was shown in the mouse monocyte/macrophage line RAW264.7 that IL-33 directly induces MMP-9 expression, which facilitates tumor progression, invasion, and angiogenesis." (PMID 30483263, 2018). "Overexpression of AT1R also accelerated tumor growth, increased tumor angiogenesis, enhanced tumor invasiveness as demonstrated by increased expression of EMT markers including matrix metallopeptidase 9 (MMP-9) and reduced E-cadherin." (PMID 28416734, 2017). "MMP-2 and MMP-9, are potent gelatinases and have been correlated with the processes of tumor cell invasion and metastasis, play an important role in the various pathologies such as development and progression of cancer." (PMID 28522860, 2017).